APOA1 (apolipoprotein A1)
Diseases named in the same sentence as APOA1 in open-access papers (continued):
Sharing a sentence is not in itself a finding about the gene and the disease.
cervical cancer (5 papers, 2019 to 2023). A primary or metastatic malignant neoplasm involving the cervix. "Functional annotation was performed using GO analysis on 1,056 differently expressed proteins to identify those that may impact cervical cancer, such as heme protein myeloperoxidase, which is involved in the immune process, and APOA1, which is associated with lipid metabolism." (PMID 33194326, 2020). "The present study aimed to preliminarily explore the function and mechanism of APOA1 in platinum-based chemoresistance in cervical cancer, and the detailed mechanism needs to be further studied." (PMID 35421932, 2022). "Literature searches were conducted to find APOA1 downstream proteins and mechanisms affecting resistance to platinum-based chemotherapy in cervical cancer." (PMID 35421932, 2022). "An investigation into APOA1 expression among cervical cancer patients, as compared to a control group, noted a significant decline in APOA1 levels in the patients, positioning it as a possible biomarker for cervical cancer." (PMID 38067270, 2023). "Although a few studies on APOA1 and tumor chemotherapy have been reported, the mechanism underlying the role of APOA1 in platinum-based chemotherapy resistance in cervical cancer has not been reported." (PMID 35421932, 2022). "However, whether APOA1 is related to chemotherapy in cervical cancer has not yet been reported." (PMID 35421932, 2022).
cervical squamous cell carcinoma (5 papers, 2020 to 2024). A squamous cell carcinoma arising from the cervical epithelium. "In patients with squamous cervical cancer, APOA1 overexpression can reduce the sensitivity of cervical squamous cells to carboplatin by regulating the expression of STAT1, CD81, C3, and TOP2A." (PMID 38212711, 2024). "Additionally, studies have shown that concentrations of APOA1, APOE, and CLU were differentially expressed in cervical squamous cell carcinoma patients when compared to those with benign lesions and were associated with the histological classification or the processing of the cervical lesion." (PMID 33521130, 2021).
Crohn disease (5 papers, 2012 to 2023). A gastrointestinal disorder characterized by chronic inflammation involving all layers of the intestinal wall, noncaseating granulomas affecting the intestinal wall and regional lymph nodes, and transmural fibrosis. "APOA1 expression is reduced in Crohn’s disease patients, and APOA1 levels inversely correlate with disease activity." (PMID 29066772, 2017). "APOA1 (Alipoprotein A-I; up-regulated in P2 and S2 in S) is typically down-regulated during Crohn’s disease." (PMID 28002487, 2016).
emphysema (5 papers, 2016 to 2024). "In contrast, overexpression of ApoA1 in the alveolar epithelium protected mice from developing cigarette-smoke-induced emphysema." (PMID 38891077, 2024). "Taken together, the data showed that ApoA1 overexpression attenuated CS-induced lung inflammation and emphysema in mice." (PMID 34574829, 2021). "Therefore, targeted augmentation of ApoA1 in the lung may have therapeutic potential by preventing smoking-related COPD/emphysema." (PMID 34574829, 2021). "ApoA1-overexpressing transgenic mice did not develop emphysema when they were exposed to chronic CS." (PMID 34574829, 2021).
endometriosis (5 papers, 2023 to 2025). The growth of functional endometrial tissue in anatomic sites outside the uterine body. "Univariable MR analysis indicated that among the five included lipid traits, ApoA-1 (OR = 0.893, 95% CI: 0.817–0.975, P = 0.013), HDL cholesterol (OR = 0.899, 95% CI: 0.824–0.981, P = 0.018) and TG (OR = 1.159, 95% CI: 1.054–1.275, P = 0.002) had causal effects on endometriosis." (PMID 38627726, 2024). "Moreover, cyto-hub gene analysis revealed that CSNK2A1, CSNK2A2, TOP1, PRKACA, RBM39 (plasma), ALB, ACTB, GAPDH, FN1, APOA1 (serum), S100-A9, CXCL1, IL1RN, CSTA, S100-A8 (menstrual blood) and THBS1, ALB, CD44, ANXA2, and LUM (urine) were the top 5 proteins expressed in women with endometriosis." (PMID 39061077, 2024). "We compared endometriosis status, stage (I/II vs III/IV), and typology to no endometriosis using adverse lipid thresholds (total cholesterol ≥200 mg/dL, HDL <50 mg/dL, LDL ≥100 mg/dL, triglycerides ≥175 mg/dL, non-HDL ≥130 mg/dL, VLDL ≥30 mg/dL, ApoA1 <125 mg/dL, and ApoB ≥120 mg/dL)." (PMID 41407106, 2025).
Hepatitis (5 papers, 2010 to 2025). Inflammation of the liver. "Furthermore, we introduced a wide range of novel predictors such as gallstones, hepatitis, osteoarthritis, apolipoprotein A1 and B100 levels, ASAT levels, ALAT levels, and many medication types, especially anti-inflammatory and antirheumatic drugs." (PMID 40741513, 2025). "This study first aimed to verifying that the ApoB/ApoA1 ratio is strongly correlated with CHB disease progression, and its predictive potential is not correlated with potential risk factors (e.g., age, anti-hepatitis treatment, and duration of chronic hepatitis)." (PMID 38744926, 2024).
hyperthyroidism (5 papers, 2011 to 2022). Overactivity of the thyroid gland resulting in overproduction of thyroid hormone and increased metabolic rate. "The serum APOA1 content observed in pregnant women with hyperthyroidism at the middle and late stages of pregnancy is significantly lower than that found in normal pregnant women." (PMID 34650432, 2021). "Lower triglycerides, HDL, apoA1, apoB, and Lp(a) levels have been found in patients with hyperthyroidism compared with euthyroid controls, which is questionable by other reports." (PMID 21789282, 2011). "Therefore, R. Scrophulariae might treat hyperthyroidism by upregulating the APOA1 and cholesterol levels while simultaneously downregulating the IL6 levels and regulating the IL6-APOA1-cholesterol pathway via the HIF signaling pathway." (PMID 34650432, 2021). "The content of APOA1 in the serum of pregnant women with hyperthyroidism at the early stage of pregnancy does not significantly differ from that found in normal pregnant women." (PMID 34650432, 2021). "The serum concentration of total cholesterol, LDL-C, non-HDL-C, triglycerides, apoA-1 and apoB were unchanged in subclinical hyperthyroidism." (PMID 32300332, 2020).
hypothyroidism (5 papers, 2014 to 2025). Abnormally low levels of thyroid hormone. "One study of 1650 pregnant women with thyroid dysfunction revealed that those with clinical hypothyroidism exhibited higher levels of apolipoprotein A1 (Apo-A1) and Apo-B than those with normal thyroid function." (PMID 39015803, 2024). "In addition, hypothyroidism impairs HDL-C synthesis by reducing apolipoprotein A1 (ApoA1) production, which is crucial for cholesterol efflux from peripheral tissues." (PMID 40831839, 2025). "However, after thyroidectomy, the serum concentrations of ApoA1 were significantly increased in hypothyroidism patients." (PMID 34784265, 2022). "Although some studies report elevated HDL-C levels in severe hypothyroidism, this may not translate into improved cardiovascular health, as HDL-C efflux capacity remains impaired due to reduced ApoA1 levels." (PMID 40831839, 2025).
injury (5 papers, 2013 to 2023). Damage inflicted on the body as the direct or indirect result of an external force, with or without disruption of structural continuity. "A hospital-based case-control study found that APOA1 -75 AA genotype was associated with a higher acute lung injury (ALI) risk after cardiopulmonary bypass (CPB) surgery." (PMID 26173491, 2015). "Recently, the ApoA1 mimetic compound has been reported to have therapeutic effect in kidney injury." (PMID 24349659, 2013).
leprosy (5 papers, 2018 to 2022). Leprosy is a chronic infectious disease affecting primarily the skin and peripheral nervous system. "High αPGL-I IgM, IP-10, and CRP levels, relative to controls, were associated with MB leprosy, whereas ApoA1 and S100A12 levels were critical for identification of both patients groups." (PMID 33490914, 2021). "Recently, a multi-biomarker test (MBT) evaluating αPGL-I IgM, IP-10, CRP, S100A12, and ApoA1 was successfully used to discriminate patients with MB and PB leprosy from control individuals in high and low leprosy endemic areas." (PMID 35416839, 2022). "Separate evaluation of biomarkers, however, indicated that ApoA1 differed significantly in these patients with PB leprosy from controls, corroborating the potential of ApoA1 as a biomarker for PB leprosy." (PMID 33490914, 2021). "M. leprae-exposed HCs in South Korea showed a similar ApoA1 response as the patients with PB leprosy, as observed previously in Bangladesh." (PMID 33490914, 2021). "Similarly, MBT data of both cohorts showed that the ApoA1 R values in patients with PB leprosy differed from those in healthy controls." (PMID 33490914, 2021). "For patients with PB leprosy, ApoA1 was identified as the most important biomarker." (PMID 33490914, 2021). "Interestingly, contacts of patients with leprosy in South Korea showed ApoA1 R values similar to those of patients with PB leprosy." (PMID 33490914, 2021). "The role and functionality of ApoA1 in leprosy thus remains to be further elucidated." (PMID 32849645, 2020). "On the other hand, by an anabolism perspective, modulation of ApoA-I levels in leprosy may be correlated to a hepatic involvement, as APOA1 gene is mainly expressed by hepatocytes." (PMID 32226013, 2020). "A host biomarker signature of αPGL-I IgM, IP-10, CRP, ApoA1, and S100A12 was identified, covering both the humoral and cellular pole of the immunopathologic leprosy spectrum." (PMID 33490914, 2021). "Unfortunately, we were not able to observe differences in apolipoprotein A1 abundance between control and leprosy clots in 2D gels, and because of this, the source of the neutral lipids contained in the leprosum clot remains a subject of investigation." (PMID 29565968, 2018).
lymph node metastasis (5 papers, 2015 to 2021). "The presence of the APOA1 +83 T allele appeared, however, to be associated with an increased risk of lymph node metastasis, but this same finding is refuted in our report." (PMID 34440141, 2021). "Combined with qPCR-based validation findings from tissue, serum and whole blood samples, they highlighted that serum exosomal proteins, PF4V1, CXCL7, F13A1 and ApoA1 may be related to the OSCC lymph node metastasis." (PMID 32054041, 2020). "The univariable analysis demonstrated that BMI, jaundice, lymph node metastasis, intrahepatic involvement, extrahepatic involvement, tumor differentiation, radical cure, R0, TG, HDL, TC/HDL, TG/HDL, ApoA1, ApoB, lipoprotein, albumin, GGT, ALP, TBIL, CA199 were associated with OS (P < 0.05)." (PMID 33036576, 2020).
malnutrition (5 papers, 2020 to 2024). Inadequate nutrition resulting from poor diet, malabsorption, or abnormal nutrient distribution. "An impact of malnutrition on apolipoprotein-A1 values, was excluded as no significant changes in weight were observed." (PMID 33216772, 2020).
meningioma (5 papers, 2014 to 2023). A generally slow growing tumor attached to the dura mater. "In the current study, we have observed an upregulation of APOE and APOA1 in GBMs when compared to LGGs and upregulation of APOE and downregulation of APOA1 in Meningioma Grade II tissue compared to Meningioma Grade I." (PMID 34055594, 2021).
neuroblastoma (5 papers, 2006 to 2023). Neuroblastoma (NB) is the most common solid, extracranial childhood tumor. "Additionally, research on neuroblastoma-associated neuronal injury models has shown that ApoA1 is initially diminished and then sharply increased in response to neuronal injury." (PMID 36600206, 2023).
osteosarcoma (5 papers, 2022 to 2024). A usually aggressive malignant bone-forming mesenchymal neoplasm, predominantly affecting adolescents and young adults. "Recent studies have found that APOC1 promotes osteosarcoma progression through binding to MTCH2, and preoperative APOB/APOA1 has been identified as an independent prognostic factor for osteosarcoma in children and adolescents." (PMID 38212768, 2024). "In osteosarcoma, circ_0088212 exhibits a cancer-promoting role by regulating the miR-520 h/APOA1 axis." (PMID 38212711, 2024). "In univariate and multivariable analyses, preoperative PAR and ApoB/ApoA1 were identified as independent prognostic factors for OS in children and adolescents with osteosarcoma." (PMID 35086516, 2022). "Further subgroup analysis was performed to investigate the prognostic value of PAR, PLR, LDL-C/HDL-C, and ApoB/ApoA1 in children and adolescent patients with osteosarcoma stratified by Enneking stage." (PMID 35086516, 2022). "Herein, this retrospective study investigated the prognostic value of preoperative PAR, PLR, LDL-C/HDL-C, and ApoB/ApoA1 in children and adolescents with osteosarcoma." (PMID 35086516, 2022). "More significantly, we confirmed that preoperative PAR and ApoB/ApoA1 can be identified as independent prognostic factors for OS in children and adolescents with osteosarcoma." (PMID 35086516, 2022). "Preoperative PAR and ApoB/ApoA1 can be used as promising predictors in children and adolescents with osteosarcoma to help clinicians recognize patients with an increased risk of poor prognosis." (PMID 35086516, 2022). "More significantly, we confirmed for the first time that preoperative PAR and ApoB/ApoA1 can be identified as independent prognostic factors for OS in children and adolescents with osteosarcoma." (PMID 35086516, 2022). "Based on this, interventions or drugs aimed at reducing the ratio of PAR and ApoB/ApoA1 might be a potentially effective strategy to improve the prognosis of osteosarcoma." (PMID 35086516, 2022). "Whereas, as new indicators for evaluating OS, the potential mechanism of serum PAR and ApoB/ApoA1 to predict the survival outcomes of osteosarcoma remains unclear." (PMID 35086516, 2022). "For example, a study demonstrated that cellular proliferation and invasion were inhibited in APOA1-overexpressed SW1353 and HOS cells, which is related to osteosarcoma progression." (PMID 38003549, 2023). "Osteosarcoma patients in high PAR group (> 4.41) and high ApoB/ApoA1 group (> 0.82) experienced significantly shorter overall survival compared with those in low PAR group (≤ 4.41) and low ApoB/ApoA1 group (≤ 0.82)." (PMID 35086516, 2022).
peripheral vascular disease (5 papers, 2021 to 2025). Any disorder affecting blood flow through the veins or arteries outside of the heart. "We found that APOE, IGF1R, HMGCR, APOA1, ENG, SERPINA3 and LCN2 were hub proteins in the network, which were also predicted to be associated with peripheral vascular disease." (PMID 37496672, 2023). "The predictors of COPD severity included vascular disorders, HDL, plasma fibrinogen, fructosamine, standard bicarbonate concentration, pCO2, age, eosinophil count, lymphocyte ratio, apolipoprotein A1, pO2, plasma carbon dioxide concentration, sex, and allergic diseases." (PMID 36590951, 2022). "The predictors of COPD severity were vascular disorders, HDL, plasma fibrinogen, fructosamine, standard bicarbonate concentration, pCO2, age, eosinophil count, lymphocyte ratio, apolipoprotein A1, pO2, plasma carbon dioxide concentration, sex, and allergic diseases." (PMID 36590951, 2022).
renal carcinoma (5 papers, 2015 to 2022). A carcinoma arising from the epithelium of the renal parenchyma or the renal pelvis. "In conclusion, to our best knowledge, up to now this study is the first to examine prospectively an increased risk role of APOA1 -75 AA genotype and APOA1 -75 A allele in renal cancer susceptibility." (PMID 26537097, 2015). "The exact biological mechanism of the association between the APOA1 -75G/A polymorphisms and the risk of renal cancer is still unclear." (PMID 26537097, 2015). "The objective of the present study was to evaluate the association of two genetic variants (−75 G/A and +83 C/T) of APOA1 with predisposition to renal cancer." (PMID 26537097, 2015). "Patients with renal cancer had a significantly higher frequency of APOA1 -75 AA genotype [odds ratio (OR) = 2.10, 95 % confidence interval (CI) = 1.18, 3.75; P = 0.01] and APOA1 -75 A allele (OR =1.40, 95 % CI = 1.05, 1.87; P = 0.02) than controls." (PMID 26537097, 2015). "This study is, to our knowledge, the first to examine prospectively an increased risk role of APOA1 -75 AA genotype and APOA1 -75 A allele in renal cancer susceptibility." (PMID 26537097, 2015). "To test this hypothesis, we performed a prospective hospital-based case–control study to evaluate the association of the APOA1 -75 G/A and +83 C/T genotypes with predisposition to renal cancer." (PMID 26537097, 2015). "Finally, further research on the biological mechanism of the association between the APOA1 -75G/A polymorphisms and the risk of renal cancer is necessary." (PMID 26537097, 2015). "We hypothesized that APOA1 -75 G/A and +83 C/T genotypes were associated with renal cancer risk." (PMID 26537097, 2015).
renal dysfunction (5 papers, 2019 to 2025). "The kidneys are major organs removing apoA-I from the body, and urinary apoA1 concentration is positively associated with renal dysfunction and renal disease over time." (PMID 35629966, 2022). "Studies have found that the plasma apoB/A1 ratio, but not apoB level, is associated with CKD progression and immunoglobulin A nephropathy, although neither apoA1 nor apoB alone is associated with renal dysfunction in heart failure." (PMID 35629966, 2022). "Decreased serum apoA1 has been demonstrated in patients with renal dysfunction." (PMID 35629966, 2022).
sarcoidosis (5 papers, 2019 to 2024). Sarcoidosis is a multisystemic disorder of unknown cause characterized by the formation of immune granulomas in involved organs. "Indeed, a number of proteins involved in lipid metabolism have been identified as contributing factors in the pathogenesis of sarcoidosis, including apoA1, fatty acid-binding protein 4/perilipin 2, 8-isoprostane, zinc-α2 glycoprotein and serum amyloid A (SAA)." (PMID 31681260, 2019).
thrombosis (5 papers, 2016 to 2023). "Lower ApoA1 levels were also correlated with lower platelet counts and higher syndecan-1 levels, suggesting that lower ApoA1 was associated with microvascular thrombosis and endothelial damage." (PMID 26830467, 2016). "The levels of APOA1 and ALB were significantly higher in patients with deep vein thrombosis than in healthy controls in un-targeted protein analysis of urine samples." (PMID 34768685, 2021).
vitamin D deficiency (5 papers, 2018 to 2025). A nutritional condition produced by a deficiency of VITAMIN D in the diet, insufficient production of vitamin D in the skin, inadequate absorption of vitamin D from the diet, or abnormal conversion of vitamin D to its bioactive metabolites. "Moreover, women with PCOS and a severe vitamin D deficiency had the lowest levels of HDL cholesterol and apolipoprotein A1." (PMID 30513089, 2018).
alcoholic liver diseases (4 papers, 2006 to 2025). A disorder caused by damage to the liver parenchyma due to alcohol consumption. "We observed a dramatic decrease in ApoA1 serum levels in patients with alcoholic liver disease which was associated with necrosis, polymorphonuclear infiltrate and Mallory bodies." (PMID 16503961, 2006).
anemia (4 papers, 2010 to 2021). A reduction in the number of red blood cells, the amount of hemoglobin, and/or the volume of packed red blood cells. "The correlation between ApoA1 and hemoglobin levels in primigravidae but not in multigravidae suggests that early PM events that may not be detected by placental histology could have a long term effect on anemia." (PMID 20098675, 2010).